MIR633 (microRNA 633)
Synonyms: hsa-mir-633; MIRN633
Gene: MicroRNA gene on chromosome 17 (62,944,215 to 62,944,312, forward strand). Ensembl gene ENSG00000207552.
Gene Ontology:
Biological process: miRNA-mediated post-transcriptional gene silencing